MDM2 (MDM2 proto-oncogene)
Diseases named in the same sentence as MDM2 in open-access papers (continued):
Sharing a sentence is not in itself a finding about the gene and the disease.
liposarcoma (continued). "The two tumor samples (primary tumor and recurrence) of one patient (cases 8a and 8b) both demonstrated PTPRB and MDM2 amplification (these cases were reevaluated to rule out liposarcoma; see Section 3)." (PMID 38791144, 2024). "The expression of MDM2 and CDK4 genes in chromosome 12q13-15 was found to be amplified in both well-differentiated and dedifferentiated liposarcoma, and immunostaining showed high sensitivity and specificity in both tumors, which can be used for differential diagnosis." (PMID 39297994, 2024). "Around 10–20% of cases may show MDM2 and CDK4 amplification, which is typically found in dedifferentiated liposarcoma." (PMID 38982521, 2024). "Nevertheless, specific miRNAs, in particular, miR-215-5p, was shown to promote MDM2 expression in liposarcoma without specificity to a certain subtype." (PMID 38254762, 2024). "Immunostaining for MDM2 and CDK4 is useful for the diagnosis of liposarcoma." (PMID 39297994, 2024). "This means that when dealing with a large retroperitoneal tumor that expresses and/or amplifies MDM2, the initial consideration should be liposarcoma rather than a neoplasm with GLI1 alteration." (PMID 38275873, 2024). "This characteristic genetic aberration helps differentiate lipoblastoma from other adipose tumors such as liposarcoma and is identified by MDM2 amplification, which was negative in our patient." (PMID 39011190, 2024). "Combining the histological morphology, immunohistochemistry, and MDM2/CDK4 FISH test results, we diagnosed the patient with ovarian mucinous cystadenoma with a mural nodule of well-differentiated liposarcoma, International Federation of Gynecology and Obstetrics (FIGO) stage IA." (PMID 39220649, 2024). "Regardless of the culture method, all liposarcoma models were diffusely or mostly positive for MDM2 staining in IHC and MDM2 DNA detection in DNAscopeTM." (PMID 38500686, 2024). "MDM2 overexpression is considered suggestive of MDM2 amplification in various malignant tumors, such as bladder carcinoma, melanoma, and liposarcoma, but it has not been evaluated in ameloblastomas." (PMID 38396916, 2024). "Simultaneously, cell lines derived from dedifferentiated liposarcomas carrying 12q13-15 region amplification (including MDM2 and CDK4 genes) represent an excellent preclinical model for the study of well-differentiated (WDLPS) and dedifferentiated (DDLPS) liposarcoma development and proliferation." (PMID 38002306, 2023). "Dedifferentiated liposarcoma could be a pitfall, given a great proportion of IMT shows MDM2 positive." (PMID 37735390, 2023). "MDM2 and CDK4 amplification is also seen in other malignant tumors, such as dedifferentiated liposarcomas, among others, which may create a differential diagnostic challenge, given the morphological, immunohistochemical, and molecular similarities." (PMID 37108696, 2023). "We considered two differential diagnoses, dedifferentiated liposarcoma lacking MDM2 amplification and myxoid pleomorphic liposarcoma (MPLPS), and determined that this case is most likely MPLPS." (PMID 36514176, 2022). "More importantly, consistent MDM2 and/or CDK4 amplification is present in dedifferentiated liposarcomas, which is absent in USP6-associated soft tissue tumors with bone metaplasia." (PMID 36727055, 2022). "FISH analysis for the detection of MDM2 gene amplifications was also performed to rule out the possibility of dedifferentiated liposarcoma, and the result was negative." (PMID 35001360, 2022). "Interestingly, MDM2 amplification and CDK4 polisomy have been observed in colorectal dedifferentiated liposarcomas." (PMID 35205133, 2022).
liposarcoma (continued). "Although no typical well-differentiated liposarcoma component was observed, MDM2, CDK4 and P16 IHC staining were diffusely positive, and MDM2 gene amplification, identified by FISH, supported the diagnosis of DL." (PMID 36123846, 2022). "MDM2 and CDK4 are known to be amplified in well‐differentiated and dedifferentiated liposarcoma." (PMID 35586877, 2022). "Negative staining of CDK4 and MDM2 ruled out well-differentiated liposarcoma and dedifferentiated liposarcoma." (PMID 34797454, 2021). "Of note, a small subset of dedifferentiated liposarcomas (DDLPS) may show expression since the STAT6 gene may be co-amplified with its neighboring genes, MDM2 and CDK4." (PMID 33921435, 2021). "However, FISH analysis for the MDM2 and CDK4 gene amplification is usually helpful in distinguishing aggressive angiomyxoma from dedifferentiated liposarcoma." (PMID 33422117, 2021). "FISH for MDM2 amplification status was performed in 61/74 cases of adipocytic neoplasms and was found to be the most useful technique for confirming or excluding a diagnosis of well-differentiated liposarcoma (WDL) or dedifferentiated liposarcoma (DDL)." (PMID 33061792, 2020). "Murine double minute 2 (MDM2) and cyclin-dependent kinase 4 (CDK4) are both coded on chromosome 12q13-15 and are known to be amplified in well-differentiated and dedifferentiated liposarcoma." (PMID 31963219, 2020). "Interestingly, similar effect was observed upon exposure to PARP inhibitor in case of liposarcoma and other tumors, however, upregulation of p21WAF1/CIP1 and proteosomal degradation of MDM2 were accompanied by downregulation of CDK4." (PMID 30734151, 2020). "Likewise, MDM2 and CDK4 are both positive in dedifferentiated liposarcoma that can thus be distinguished from SFT." (PMID 32566457, 2020). "MDM2 and CDK4 were both positive in dedifferentiated liposarcoma cases used as controls." (PMID 32566457, 2020). "Novel targeted therapies involving MDM2 and CKD4 inhibitors are currently being evaluated and may change the landscape of systemic therapy for liposarcomas in the future." (PMID 31280066, 2019). "Other than the pathognomonic MDM2 amplification in liposarcoma, there were no altered genes that clustered into specific histologic types (top colored bar)." (PMID 31528332, 2019). "MDM2 inhibitors under investigation have demonstrated responses in early phase clinical trials in MDM2 amplified soft tissue sarcomas (with or without CDK4 co-amplification) such as liposarcoma and synovial sarcoma." (PMID 31480474, 2019). "The cells have a gain on chromosome 12, including CPM and MDM2 which is consistent with liposarcomas, but not highly amplified, which rules out a well-differentiated/de-differentiated liposarcoma subtype." (PMID 29570692, 2018). "Concomitant alterations of MDM2 and CDK4 are known and have been described in liposarcoma." (PMID 30237864, 2018). "MDM2 and CDK4/6 are highly amplified in well-differentiated/dedifferentiated liposarcoma." (PMID 29510588, 2018). "The sequencing results also help confirm the liposarcoma subtype based on the presence or absence of MDM2 amplification, when it is not clear on imaging and histopathology." (PMID 29731991, 2018).
liposarcoma (continued). "In brief, the current study results indicated that FISH analysis of MDM2 amplification and CHOP rearrangement in liposarcomas and SYT rearrangement in synovial sarcomas, as well as histopathological findings, were helpful to differentiate such sarcoma subtypes." (PMID 29531545, 2017). "There was no MDM2 amplification (MDM2/Cep12 ratio of 1.0), thus, the diagnosis of dedifferentiated liposarcoma was excluded." (PMID 29292724, 2017). "MDM2 and CDK4 (12q13-15 amplification) are co-amplified in well differentiated liposarcoma." (PMID 28424409, 2017). "There is no literature on the role for MDM2 fluorescent in situ hybridization studies in distinguishing between a well-differentiated liposarcoma with extreme fibrosis and a fibrosing inflammatory pseudotumor." (PMID 26987706, 2016). "Amplification of this region and/or specific genes found in this region (e.g., MDM2) can be detected by fluorescence in situ hybridization (FISH), and this test is used to establish diagnosis of WD/DD liposarcoma in cases in which diagnosis cannot be made on histology alone." (PMID 27376027, 2016). "For example liposarcoma which is the most common type of soft tissue sarcoma in adults, accounting for approximately 20% of all adult soft tissue sarcomas, is characterized by amplifications of CDK4 and MDM2." (PMID 26887042, 2016). "The differential diagnosis for dedifferentiated liposarcoma and Rhabdoid tumor were dismissed by immunohistochemical analysis that showed negative staining for MDM2, CDK4, p16 and positive staining for BAF47(INI1)." (PMID 26208724, 2015). "However, these profiles did not segregate by histology (lung adenocarcinoma-appendiceal cancer (KRAS G12D and GNAS R201C), and lung adenocarcinoma-liposarcoma (CDK4 and MDM2 amplification pairs))." (PMID 26418953, 2015). "In this study, we sought to identify factors associated with tumor recurrence and patient survival including the levels of MDM2 and CDK4 amplification in a homogeneous population of patients with WD and DD liposarcomas of the abdomen undergoing complete surgical resection." (PMID 25121597, 2014). "MDM2 IHC analyses were not carried out because we have seen from past reports that MDM2 was almost ubiquitously overexpressed in WD and DD liposarcomas and therefore did not affect tumor biology." (PMID 25121597, 2014). "Case 4 with negative staining for CD34 and absence of a detectable gene fusion showed strong nuclear expression of STAT6 and no MDM2 amplification, so the possibility of being a dedifferentiated liposarcoma was ruled out." (PMID 25432794, 2014). "We suggest that the presence or absence of a well-differentiated liposarcoma component and expressions of MDM2 and CDK4 should be considered in the diagnosis of IMTs and requires further research." (PMID 25022487, 2014). "While MDM2 amplification and overexpression is present in most WD and DD liposarcomas, CDK4 amplification is absent in a small proportion of cases." (PMID 25121597, 2014). "The diagnosis of a well-differentiated liposarcoma was suspected but molecular cytogenetic analyses showed no MDM2 or CDK4 gene amplification on fluorescent in situ hybridization and the diagnosis of a benign lipoma was confirmed." (PMID 24363942, 2013). "Diagnosis of a well-differentiated liposarcoma was suspected and molecular cytogenetic analyses showed no MDM2 nor CDK4 gene amplification on fluorescent in situ hybridization." (PMID 23308321, 2012).
liposarcoma (continued). "In contrast, amplifications of Mdm2 and/or Cdk4 (which were additionally tested because of their frequent amplification in human sarcomas, most prominently liposarcomas) were rare (<5%; not shown)." (PMID 21533183, 2011). "The remaining 42 (97.7%) cases, although had overlapping morphologic features with our well-differentiated liposarcoma case, were negative for MDM2 gene amplification by FISH with a corresponding final diagnosis of spermatic cord lipomas with reactive-type atypia." (PMID 40799874, 2025). "Amplification of MDM2 and positivity for CDK4 are more characteristic of well-differentiated liposarcomas in particular, and though a small percentage can be positive for STAT6, that marker is more specific for solitary fibrous tumors (SFTs) or dedifferentiated liposarcomas." (PMID 41141132, 2025). "The absence of amplification of MDM2 can help distinguish pleomorphic liposarcoma from DDLPS." (PMID 39735679, 2025). "However, neither giant cells nor lipoblasts were detected by histology and the lack of simultaneous CDK4- plus MDM2-amplification ruled out an atypical lipomatous tumor/well-differentiated liposarcoma." (PMID 38681749, 2024). "Pathologists and clinicians should be aware that not all huge fatty tumors in the retroperitoneum are well-differentiated liposarcomas and the use of FISH assay on routine paraffin section for MDM2 amplification could effectively and reliably confirm the diagnosis of lipoma in the retroperitoneum." (PMID 37131332, 2024). "In one well-differentiated liposarcoma sarcoma, MDM2 amplification is not identified." (PMID 37627196, 2023). "Given the almost universal amplification of MDM2 in WDLPS and DDLPS, detection of this genomic aberration in ctDNA could be clinically useful for non-invasive distinction between these liposarcomas and other retroperitoneal tumors in the appropriate clinical context." (PMID 34986184, 2022). "Dedifferentiated liposarcoma is a high-grade non-lipogenic sarcoma that arises in a background of a pre-existing well-differentiated liposarcoma, harbouring a genomic amplification in the 12q13–15 region constituting the MDM2, CDK4 and HMGA2 genes." (PMID 29621151, 2018). "However, attempts to treat liposarcoma patients with MDM2 antagonists have so far not yielded the expected clinical success." (PMID 30206211, 2018). "Thus a pre-operative biopsy was performed along with MDM2 gene amplification to rule out a liposarcoma preceding surgical excision." (PMID 28088193, 2017). "In addition, mdm-2 amplification remains a robust marker for liposarcoma and has not been reported in SFT." (PMID 26358059, 2015). "However, a recent study reported that peripheral UPS with MDM2 gene amplification is considered DDLS even if there is no well-differentiated liposarcoma area." (PMID 26502919, 2015). "Therefore the presence or absence of a well-differentiated liposarcoma component and expression of MDM2 and CDK4 should be considered in the diagnosis of IMTs and requires further research." (PMID 25945274, 2015). "ALT/WDL and dedifferentiated liposarcomas (DDL) most often have a supernumerary ring and giant marker chromosomes composed of amplified sequences from the 12q13-15 region, including the murine double-minute type 2 gene (MDM2) and the cyclin-dependent kinase 4 gene (CDK4)." (PMID 24965044, 2014). "However, previous analysis of MDMX over-expression and of its relative co-expression with MDM2 in human liposarcomas is lacking." (PMID 24330579, 2013). "Interestingly, also the MFH/UPS, the leiomyosarcomas and the fibrosarcoma that clustered tightly with the dedifferentiated/pleomorphic liposarcomas showed amplification of CDK4 and MDM2 when analyzed by array comparative genomic hybridization (data not shown) or Southern blot analysis." (PMID 17359542, 2007).
liposarcoma (continued). "Moreover, it was shown that degradation of MDM2 in response to palbociclib exposure was critical for the induction of senescence hallmarks, since the persistence of MDM2 resulted in palbociclib-exposed liposarcoma cells entering into a quiescent, rather than a senescent, growth arrest." (PMID 32235364, 2020). "Histopathology confirmed benign lipomatosis with CDK4(+), MDM2(+), Ki-67 (+,2%), and negative MDM2 amplification on fluorescence in situ hybridization (FISH), arguing against well-differentiated liposarcoma." (PMID 41869673, 2026). "Genetic findings in ESOS are nonspecific; approximately 10–20% of cases exhibit MDM2 and CDK4 amplification, typically seen in dedifferentiated liposarcoma." (PMID 40308507, 2025). "On the other hand, well-differentiated liposarcomas consist of atypical, hyperchromatic stromal cells and are negative for CD34 and positive for MDM2 and CDK4." (PMID 40777097, 2024). "ASPLTs show no MDM2 or CDK4 amplification, which distinguishes them from atypical lipomatous tumor (ALT)/well-differentiated liposarcomas (WDLPS), and dedifferentiated liposarcomas (DDLPS)." (PMID 36983010, 2023). "We first confirmed expression of CDK4 and MDM2 as established biomarkers of WDLPS and DDLPS and determined that both markers were highly expressed in the liposarcoma cell lines regardless of adipogenic potential when compared to normal HuASC primary cells." (PMID 35313831, 2022). "MDM2 and CDK4 nuclear staining is not a characteristic of benign lipomatous tumors in well-differentiated and dedifferentiated liposarcomas; however, it should be noted that it is not encountered in myxoid and round cell pleomorphic liposarcomas." (PMID 31282548, 2020). "The molecular profile can also help confirm the diagnosis of WD/DD liposarcoma in those cases where histopathology is not enough to provide an accurate subtype classification and FISH for MDM2 is not available." (PMID 29731991, 2018). "By contrast, liposarcomatous differentiation in PTs is not underpinned by amplification of the MDM2/CDK4 locus, which is a well‐characterized driver of well‐differentiated and dedifferentiated liposarcomas and frequently detected in uterine adenosarcomas." (PMID 28267263, 2017). "Histopathology confirmed a lipoma with a negative MDM2 gene amplification by FISH, thus ruling out liposarcoma." (PMID 28088193, 2017). "Dedifferentiated liposarcoma, which shows the similar morphology to SFT on microscopy, was differentiated because IHC for MDM2 and CDK4 was negative in the present case." (PMID 26337721, 2015). "To date, we are not aware of any study that has described the patterns of MDM2 and MDMX co-expression in liposarcomas." (PMID 24330579, 2013). "High levels of MDM2 mRNA have been reported as a negative prognostic factor in STS, including liposarcomas." (PMID 24330579, 2013). "Although the case showed MDM2, CDK4, and DDR2 gene amplification, which were genetically similar to liposarcoma, upon microscopic examination, neither the primary nor the recurrent IMTs presented as liposarcoma." (PMID 32195970, 2020). "Since MDM2 and CDK4 amplifications are present in both well-differentiated and dedifferentiated liposarcoma, the presence of these amplifications as such are not triggers for dedifferentiation in liposarcomas." (PMID 25713799, 2015). "Finally, we confirmed the expected overexpression of some genes: KIT and ANO1/DOG1 in GISTs, MDM2 and CDK4 in non-myxoid/round cells liposarcomas, CALD1 and tropomyosin genes (TPM1, TPM2) in leiomyosarcomas, PDGFB in DFSPs, MUC1/EMA in synovial sarcomas, and CD34 in SFTs." (PMID 23734203, 2013). "However, MDM2 and CDK4 are not specific markers for liposarcoma." (PMID 23971887, 2013).